TNF (tumor necrosis factor)
Diseases named in the same sentence as TNF in open-access papers (continued):
Sharing a sentence is not in itself a finding about the gene and the disease.
endometriosis (continued). "Although we found potential importance of the ratio TNFα/CCL27 for separating patients with minimal/mild endometriosis from the control group of patients, the accuracy achieved by the algorithm was insufficient." (PMID 31723213, 2019). "The levels of inflammatory cytokines, such as interleukin-6 (IL-6), interleukin-1β (IL-1β) and tumor necrosis factor alpha (TNF-α), are increased in the follicular fluid of patients with endometriosis." (PMID 31066787, 2019). "IL-8, a chemoattractant for macrophages and neutrophils, is vigorously secreted from the peritoneum of women with endometriosis upon stimulation by IL-1 and TNF-α." (PMID 31636643, 2019). "TNF-α or IL-6 levels in serum and peritoneal fluid samples played a role in endometriosis-related pelvic inflammation." (PMID 31088412, 2019). "The expression levels of interleukin (IL)-1β, IL-6 and tumor necrosis factor (TNF)-α in lesion, endometriotic cyst fluid, and PF have been demonstrated to be increased in women with endometriosis." (PMID 31888633, 2019). "Elevated serum IL-6 and TNF-α levels indicative of increased inflammatory activity have been observed in patients with endometriosis." (PMID 30555421, 2018). "Transcriptomic work on endometriomas showed that the inflammatory cytokine transforming growth factor beta 1 (TGFβ1), regulates other inflammatory mediators relevant to endometriosis, including tumor necrosis factor alpha (TNFα) and interleukin-6 (IL6)." (PMID 30087267, 2018). "An increase in TNFα expression was noted in the PF from infertile women with endometriosis compared to that from normal women." (PMID 31417983, 2018). "The two main components, oureirin and ginsenoside R, were shown to be effective in reducing the level of VEGF and TNF-α in the peritoneal fluids in an endometriosis rat model." (PMID 30402122, 2018). "In our opinion, there is a possibility that TNF-α serum levels may become a marker used for clinical verification in the case of problematic differentiation (UF or different tumor), or to determine the risk of clinical symptoms, as can be partially done with endometriosis." (PMID 30518097, 2018). "Elevated pro-inflammatory cytokines IL-1β, TNF-α, and IL-6 are indicative of an inflammatory microenvironment for the follicles and gametes and embryos of endometriosis patients." (PMID 30555421, 2018). "Resveratrol has been reported as a potent antiinflammatory compound activating AMPK-SIRT1 pathway and it has been suggested to supress TNF-α-induced IL-8 release from the endometrial stromal cells via SIRT1 pathway in endometriosis." (PMID 29958542, 2018). "Previous studies showed that serum of women with endometriosis had higher concentrations of IL-10, TNF-α, and TGF-β, and administration of these cytokines, such as IL-10, promoted the growth of endometriotic lesions in a murine model." (PMID 30276219, 2018). "Nonsteroidal anti-inflammatory drugs (NSAIDs) are widely used to treat endometriosis-TNF-α-related symptoms." (PMID 30518097, 2018). "The PF of women with endometriosis contains a variety of inflammatory mediators, including Tumor Necrosis Factor α (TNFα), Interleukin-6 (IL-6), and Interleukin-8 (IL-8)." (PMID 31417983, 2018). "Encouragingly, treatment of a syngeneic mouse model of endometriosis with a long-acting TNFα-blocking agent decreased endometriotic implant size." (PMID 30087267, 2018). "While the immediate effect of antalarmin in inflammatory molecules was not the main objective of our current experiments, we recognize that inflammatory activity mainly via TNF-α, IL-6, IL-1β, among others has a significant role in endometriosis." (PMID 30427841, 2018). "The findings of increased TNFα expressions in bovine COC cultured in PF from infertile women with endometriosis suggest that TNFα from PF enters the COC and is active." (PMID 31417983, 2018).
endometriosis (continued). "We noted an increasein the number and activity of macrophages secreting proinflammatorycytokines interleukin-1 (IL-1) and tumornecrosis factor (TNF) in women with endometriosis." (PMID 29043703, 2018). "TNF-α levels in the peritoneal fluid are higher in women with endometriosis (higher stages of endometriosis correspond to higher TNF-α levels)." (PMID 30518097, 2018). "In this study, the relationship of three variables was also examined using regression analysis and revealed a significant association among TNFα, GDF-9, and KitL expression cultured in PF from infertile women with endometriosis added with curcumin (p< 0.05)." (PMID 31417983, 2018). "A marked increase in TNF-α concentration in granulosa cell cultures of women with endometriosis has been demonstrated." (PMID 29373970, 2018). "In women with endometriosis, inflammatory mediators including interleukin (IL)-1β, IL-6, tumor necrosis factor (TNF)-α, prostaglandins (PGs) and nerve growth factor (NGF) have been demonstrated to be elevated in peritoneal fluid and/or endometriotic lesions." (PMID 28898282, 2017). "Similar to our study, also other authors reported elevated serum concentrations of TNF-alpha in women with endometriosis and ovarian cancer." (PMID 28376925, 2017). "We decided to test sPIF effect on cell viability in the presence of TNFα as TNFα was identified as one of the pivotal chemokines involved in endometriosis and cell death." (PMID 28902871, 2017). "In contrast to endometriosis, ovarian malignancies are characterized by elevated peritoneal fluid concentrations of IL-10 and TNF-alpha, elevated serum concentrations of IL-10 and low serum levels of TNF-alpha." (PMID 28376925, 2017). "This assumption is supported by similar findings in both endometriosis and GH-PE, including activation of macrophages, increased production of cytokines such as IL-6, TNF-α, lipid peroxidation, and growth factors, and modulated NK cell activity." (PMID 28715497, 2017). "Oxidative stress offers a plausible mechanism to link inflammation and infertility as IL-1β and TNF-α are able to activate apoptotic mechanisms and oocytes from women with endometriosis have exhibited increased rates of apoptosis in the cumulus cells." (PMID 27740937, 2017). "Previous therapies for endometriosis have targeted downstream, end products such as levels of estrogen, TNF-α and COX-2." (PMID 27740937, 2017). "Unfortunately, these early studies on anti-TNF-α therapy were conducted prior to the validation of rodent models of pain assessment in animals with experimentally induced endometriosis." (PMID 26949527, 2016). "The levels of the inflammatory cytokines IL-6, IL-8, IL-1b, IFN-γ, and TNF-α increase in the PF of patients with endometriosis, which is consistent with the elevated levels noted in the serum." (PMID 27294113, 2016). "Based upon these observations, initial studies evaluated the efficacy of targeting TNF-α as a potential treatment for endometriosis." (PMID 26949527, 2016). "This study aimsto assess an association between the -1031 T/C, -238 G/A and -308 G/A polymorphismsof the TNF-α gene promoter region to endometriosis." (PMID 26644856, 2015). "The relationship between TNF-α and endometriosis has been indicated in several studies making it a good candidate gene." (PMID 26644856, 2015). "Harada and colleagues found increased levels of TNF-α in the PF of women with endometriosis and detected a positive correlation between TNF-α concentrations and endometriotic lesion size." (PMID 26247027, 2015). "A plethora of cytokines has been assessed in the search for a noninvasive diagnosis of endometriosis, including IL-1, IL-6, IL-8, TNF-α, MCP-1, and interferon-γ (IFN-γ)." (PMID 26240814, 2015). "Study has shown that several products of the immune system such as interleukin-1 ( IL-1 ), IL-6 and TNF-α play an important role in the establishment and maintenance of endometriosis." (PMID 26644856, 2015).
endometriosis (continued). "Increasing levels of IL-1β and TNF-α would induce the production of IL-6 by peritoneal mesothelial cells, which would further contribute to the local inflammation observed in endometriosis." (PMID 26247027, 2015). "Many studies on the role of other biomarkers in endometriosis (e.g., TNF-α, IL-6, VEGF, and CRP) have been conducted recently." (PMID 25006484, 2014). "In our study, compared with the disease-free controls, the eutopic endometrium from women with endometriosis showed an increased basal production of IL-6 and TNF-α, which both play a prominent role in a number of chronic inflammatory conditions." (PMID 24173391, 2014). "MMP-1, -2, -3, -7, and -9 are upregulated in endometriosis and their expression is induced by cytokines such as IL-1, IL-8, and TNF-α." (PMID 24927773, 2014). "Treatment with anti-TNF therapy (etanercept) has been evaluated in baboon with spontaneous endometriosis." (PMID 25165691, 2014). "It has been observed that TNF-α can stimulate the adhesion of endometrial cells and the proliferation of ectopic and eutopic endometrial tissues in women with endometriosis." (PMID 25165691, 2014). "In fact, increased levels of inflammatory cytokines such as interleukin-6 (IL-6), interleukin-8 (IL-8), and tumor necrosis factor-alpha (TNFα) have been observed in the peritoneal fluid in patients with endometriosis." (PMID 25331066, 2014). "The study showed that the mRNA expression of the chemokines ENA-78 and RANTES, as well as the inflammatory cytokines TNFα and IL-6, was significantly increased in the ectopic lesion compared to those in the matched eutopic tissue in women with endometriosis." (PMID 24453419, 2013). "Increased levels of lipid peroxidation markers in peritoneal fluids of women with endometriosis, like tumor necrosis factor (TNF) α, were found in previous published studies." (PMID 23799909, 2013). "A large body of evidence indicates that TNFα and IL1β, typical inflammatory cytokines, are involved in macrophage activation, inflammatory change, and enhanced angiogenesis to develop endometriosis." (PMID 23843796, 2013). "According to the literature, elevated levels of TNF-α in peritoneal fluid of patients with endometriosis stimulate the adhesion and implantation of ectopic endometrial cells to the peritoneal walls." (PMID 24298555, 2013). "These factors are present in PF as well as in endometriotic implants, and TNF-α in particular is regarded as a critical regulatory molecule in eliciting inflammatory immune responses in endometriosis." (PMID 23843796, 2013). "MUC2 expression was reported to be regulated by many endometriosis-related cytokines, such as IL-1β, IL-6, TNF-α, NF-Kappa B." (PMID 22417007, 2012). "In a mouse model of endometriosis, it was reported that interleukin-6 (IL-6) together with tumor necrosis factor alpha (TNF-α) was secreted by macrophages, and resulted in upregulation of VEGF from infiltrating neutrophils and macrophages." (PMID 20085636, 2010). "Studies in the rat and baboon have targeted TNFα activity for the prevention and treatment of endometriosis." (PMID 17118171, 2006). "Many studies have shown aberrant levels of cytokines in the peritoneal cavity of women with endometriosis compared to those of control women, including IL-1, IL-6, IL-10, p40, tumor necrosis factor-α (TNFα), and transforming growth factor-β (TNFβ)." (PMID 17118171, 2006). "The deleterious effects of TNF-α cytokines and reactive oxygen species, which were increased in the peritoneal fluid of patients with endometriosis and unexplained infertility, were prevented, by the rinsing procedure." (PMID 16018814, 2005). "Some studies indicate the role of TNF-α, IL-6, and IL-8 in the development of endometriosis." (PMID 40507929, 2025). "Notably, taking into account that increased levels of TNF-α facilitate the implantation of ectopic endometrial tissue, this protein can be established as a factor related to the development of endometriosis." (PMID 40725086, 2025).
endometriosis (continued). "Patients with endometriosis exhibit systemic monocyte activation: their spontaneous and induced production of proinflammatory cytokines TNF-α, IL-6, and IL-8 is elevated with normal levels of anti-inflammatory IL-10, indicating a proactive state of the monocyte-macrophage system." (PMID 41488658, 2025). "Moreover, there was significantly higher TNF-α secretion by peritoneal macrophages in patients with proven endometriosis compared to the control group." (PMID 40507929, 2025). "Still, another mechanism may be decreased progesterone receptor B/A ratio by treatment with either TNF-α or peritoneal fluids in women with advanced stage endometriosis." (PMID 40507929, 2025). "All endometriosis forms share core immunopathogenetic mechanisms: macrophage accumulation with M2 polarization, reduced NK cytotoxicity, elevated pro-inflammatory cytokines (IL-1β, IL-6, TNF-α) alongside immunosuppressive mediators (IL-10, TGF-β)." (PMID 41488658, 2025). "Additionally, they found that TNF-α and IL-6 levels were reduced in Alchemilla-treated endometriosis group." (PMID 40550985, 2025). "Additionally, B5 derivatives decrease tumor necrosis factor-alpha (TNF-α) levels and reduce oxidative stress in patients with endometriosis." (PMID 40469981, 2025). "We assessed the mRNA levels of EZH2, ERα, ERβ, and TNFα in endometriosis lesions." (PMID 40630095, 2025). "IL-1 generally regulates inflammation and, together with TNF-α and IL-6, has been found to promote multiple aspects of endometriosis, including inflammation, nerve growth factor expression, angiogenesis, and the growth and adhesion of ectopic endometrial tissue." (PMID 40724945, 2025). "Analysis of upstream pathway activity revealed that estrogen, TNF-α, MAPK/ERK, and PI3K/Akt are pertinent to the hormonal and immunological responses associated with menstrual illnesses such as endometriosis, polycystic ovarian syndrome (PCOS), and menorrhagia." (PMID 40028534, 2025). "Dairy, which contains progesterone, estrogen, calcium, vitamin D, and anti-inflammatory components, may lower the chance of developing endometriosis by decreasing inflammatory markers such as TNF-a, reactive oxygen species, and interleukin-6 (IL-6)." (PMID 40565701, 2025). "Moreover, it suppresses inflammatory mediators like NFκB and TNF‐α, which are known to perpetuate endometrial lesions in endometriosis." (PMID 39803270, 2025). "These therapies may also be beneficial in treating endometriosis, where targeting TNF-α has been shown to reduce inflammation and improve fertility outcomes in some patients." (PMID 41377340, 2025). "Among the best-characterized variants, the TNF-α-308G > A (rs1800629) polymorphism has been linked to elevated circulating TNF-α levels and increased endometriosis risk, with some studies suggesting a stronger association in individuals with earlier symptom onset." (PMID 41462999, 2025). "In cases of endometriosis, however, elevated levels of cytokines in the peritoneal fluid, such as interleukin (IL)-6, IL-1β, IL-8, tumor necrosis factor (TNF)-α, and transforming growth factor (TGF)-β, contribute to the development of a chronically inflamed peritoneal environment." (PMID 40692689, 2025). "We hypothesize that TNF-stimulated macrophage production of MMP9 represents one potential mechanism underlying the generation and maintenance of endometriosis." (PMID 39544239, 2024). "There is evidence that indicates an aberrant function of the TNF system in endometriosis." (PMID 38785987, 2024). "Furthermore, the study suggested that women with endometriosis-related infertility presented increased levels of TNF-α, IL-1, IL-6, IL-10, TGF-β1, and IL-8 in peritoneal fluids." (PMID 38813329, 2024).
endometriosis (continued). "While abundant cytokines and chemokines have been observed in the pelvic cavity of endometriosis patients, TNFα, IL-1β, and IL-6 are considered the key factors involved in maintaining the aberrant peritoneal inflammatory environment, promoting lesion growth, and mediating peripheral sensitization." (PMID 39192982, 2024). "Numerous studies have shown increased concentrations of interleukins (IL-1, IL-6, IL-8, and IL-33), tumor necrosis factor-alpha, insulin-like growth factor 1, and vascular endothelial growth factor in endometriosis patients, among endometriosis lesions and peritoneal fluid." (PMID 39136014, 2024). "TNF-α levels are elevated in the PFs of both patients and rat models of endometriosis." (PMID 38612685, 2024). "The increase in IL-1β and TNF-α could stimulate peritoneal mesothelial cells to produce IL-6, thereby exacerbating the local inflammation observed in endometriosis." (PMID 38928175, 2024). "Notably, TNF-α played a critical role in mediating the embryotoxicity of peritoneal fluid in endometriosis patients, mimicking its effects, and can be effectively mitigated by TNF-α inhibitors." (PMID 38542336, 2024). "Anti-TNF drugs (infliximab and etanercept) have the potential to inhibit inflammation; however, there are insufficient data to support their use specifically for endometriosis." (PMID 38543097, 2024). "Alterations in hormonal levels and increased exposure to cytokines, such as TNF-a and ROS, are other factors that may negatively influence early embryo morphokinetic events of patients with endometriosis." (PMID 38063893, 2024). "TNF-α plays a significant role in the formation and development of endometriosis implants." (PMID 39767772, 2024). "TNF-α in peritoneal fluid showed 100% sensitivity and 89% specificity for diagnosing endometriosis." (PMID 39767772, 2024). "The severity of endometriosis is strongly influenced by the serum levels of TNF-α." (PMID 39767772, 2024). "Additionally, IL-6 and TNFα facilitate adhesion of endometrial cells to the peritoneum, contributing to disease progression in endometriosis." (PMID 37834449, 2023). "Inhibition of TNF levels seemed to have beneficial effects on endometriosis." (PMID 37138868, 2023). "Women with endometriosis have elevated levels of certain cytokines, including TNFα, that can stimulate EC proliferation, survival, migration, and adhesion to the peritoneal cavity, angiogenesis, and inflammation, which ultimately promote progression of the disease." (PMID 37205467, 2023). "At the phyla level, a higher abundance of Proteobacteria in peritoneal fluid could be seen among infertile patients with endometriosis, in which several inflammatory factors, including IL-6, IL-10, IL-13, and TNF-α, may be involved." (PMID 37764164, 2023). "Another study investigated whether induction of TNFα leads to dysregulation of miRNA expressions, which are related to the NF-κB signaling pathway and contribute to inflammation in endometriosis." (PMID 37834449, 2023). "Moreover, a previously published study identified important proangiogenic factor such as vascular endothelial growth factor (VEGF), IL-1β, IL-6 and IL-8 as well as TNF-α played important roles in the vascularization process in endometriosis." (PMID 37033937, 2023). "The TNF-α/TNFR system is involved in endometriosis (EDT), a gynecologic estrogen-dependent disease." (PMID 37365216, 2023). "TNF-α has long been reported as an important tool in the diagnosis of endometriosis." (PMID 37630196, 2023). "Previous research suggested that estrogen can encourage the evolution of endometriotic lesions and have a role in the pathogenesis of endometriosis by stimulating MCs, which may increase the release of TNF-α and quicken the disease’s progression." (PMID 36982152, 2023).